DDIT4L (DNA damage inducible transcript 4 like)
Description:
Inhibits cell growth by regulating the TOR signaling pathway upstream of the TSC1-TSC2 complex and downstream of AKT1.
Synonyms: REDD2; RTP801L
Tractability: Antibody: the Human Protein Atlas places it where antibodies can reach.
Gene: Protein-coding gene on chromosome 4 (100,185,870 to 100,190,782, reverse strand). Ensembl gene ENSG00000145358.
Subcellular location: Cytoplasm
Subcellular location (Human Protein Atlas): Plasma membrane; Actin filaments; Nucleoplasm
Gene Ontology:
Molecular function: protein binding
Biological process: negative regulation of signal transduction
Cellular component: cytoplasm
Genetic constraint (gnomAD): Loss-of-function variants: 13 observed, 16.33 expected, observed/expected ratio (o/e) 0.8, 90% interval 0.52 to 1.27. The upper end of that interval is the gene's LOEUF score, 1.27, which puts it in group 5 of 6, group 1 being the genes least tolerant of losing a copy. Missense variants: 235 observed, 236.23 expected, observed/expected ratio (o/e) 0.99, 90% interval 0.89 to 1.11. Synonymous variants: 80 observed, 87.74 expected, observed/expected ratio (o/e) 0.91, 90% interval 0.76 to 1.1.
Homologues: Orthologues: macaque DDIT4L (100% identical), chimpanzee DDIT4L (99% identical), rabbit DDIT4L (93% identical), dog DDIT4L (93% identical), mouse Ddit4l (93% identical), pig DDIT4L (90% identical), rat Ddit4l (81% identical), guinea pig DDIT4L (61% identical), tropical clawed frog ddit4l (35% identical), Drosophila melanogaster chrb (27% identical), Drosophila melanogaster scyl (25% identical). Paralogues in human: DDIT4 (31% identical).
Diseases named in the same sentence as DDIT4L in open-access papers:
DDIT4L is named in the same sentence as 32 diseases in open-access papers, as found by Europe PMC text mining. Sharing a sentence is not in itself a finding about the gene and the disease. The quoted sentences say what the papers report.
melanoma (6 papers, 2013 to 2025). A malignant, usually aggressive tumor composed of atypical, neoplastic melanocytes. "DDIT4L was previously studied in melanoma patients as a risk factor, with a hypermethylated promoter." (PMID 23324053, 2013). "Promoters of COL1A2, HSPB6, NPM2, MT1G or DDIT4L were identified as hypermethylated in melanoma cells suggesting that they can be used as predictors for melanoma progression." (PMID 40427015, 2025). "The link between both genes was supported by analyzing published datasets, which revealed reduced DDIT4L expression in melanocytes and melanoma cells after siRNA-mediated knockdown of MITF." (PMID 40918647, 2025). "demonstrate that the promoter methylation level of DDIT4L is predominantly detected in advanced-stage tumors and it can be useful for evaluating melanoma tumor progression." (PMID 35646656, 2022). "Interestingly, in cases where DDIT4L expression was detectable in TCGA primary melanomas, DDIT4L correlated with MITF." (PMID 40918647, 2025). "Interestingly, the corresponding gene DDIT4L belongs to a set of genes, whose promoter is strongly methylated in melanoma." (PMID 40918647, 2025). "Analysis of the TCGA skin cutaneous melanoma gene expression dataset revealed that higher DDIT4L expression is significantly associated with longer survival probability, thus implying that DDIT4L/REDD2 may have a tumor-suppressive function in melanoma." (PMID 40918647, 2025). "The results were validated by bisulfite sequencing of COL1A2, NPM2, HSPB6, DDIT4L, and MT1G promoters, which exhibited increasing incidence with advanced melanoma stage, suggesting potential use as predictors of melanoma progression." (PMID 28396701, 2017). "It identified 76 differentially methylated markers, most of which—89% (68/76), were hypermethylated, and only a minority was previously reported in melanoma at the time (COL1A2, RAB33A, DDIT4L, and HOXB13)." (PMID 28396701, 2017). "Apparently, although MITF serves as a positive regulator of Ddit4l, elevated MITF activity did not enable substantial REDD2 expression in R722W melanocytes, indicating that additional factors contribute to REDD2 expression in R722W melanoma cells." (PMID 40918647, 2025). "To test whether REDD2 also impairs the viability of human melanoma cell lines, we expressed DDIT4L in SK-MEL-28 and UACC-62 cells, which are devoid of endogenous REDD2 expression." (PMID 40918647, 2025).
cardiac hypertrophy (4 papers, 2018 to 2023). "Furthermore, DDIT4L expression is reported in pathological cardiac hypertrophy, and overexpression of DDIT4L increases autophagy and causes mild systolic dysfunction." (PMID 38003044, 2023). "Studies have identified the expression of DDIT4L to promote myocardial hypertrophy in response to stress." (PMID 35268153, 2022). "Ddit4l is an autophagy mediator in the heart through mTOR pathways and the balance regulates both physiologic and pathological cardiac hypertrophy." (PMID 33042024, 2020). "Simonson found that DDiT4L promotes autophagy and inhibits pathological cardiac hypertrophy in response to stress by inhibiting mTOR-signaling pathways." (PMID 29391491, 2018).
glioma (3 papers, 2022 to 2026). A benign or malignant brain and spinal cord tumor that arises from glial cells (astrocytes, oligodendrocytes, ependymal cells). "However, the expression and methylation level of DDIT4L in glioma are barely reported." (PMID 35646656, 2022).
periodontitis (2 papers, 2024 to 2025). An acute or chronic inflammatory process that affects the tissues that surround and support the teeth. "Three overlapping genes (FAM46C, CFI, and DDIT4L) were identified as the most effective diagnostic biomarkers for both periodontitis and MS by using a Venn diagram." (PMID 38218802, 2024). "Then, it was discovered that CFI, DDIT4L, and FAM46C are useful diagnostic markers for periodontitis and MS." (PMID 38218802, 2024). "Further studies found that three candidate biomarkers (FAM46C, CFI, and DDIT4L) expression levels were all upregulated in both periodontitis and MS samples." (PMID 38218802, 2024). "LASSO analysis indicated that CFI, DDIT4L, and FAM46C were the most effective shared diagnostic biomarkers for periodontitis and MS, which were further validated by qPCR and immunohistochemical staining." (PMID 38218802, 2024). "Results of our study discovered that the most significant crosstalk genes between periodontitis and MS were FAM46C, SLC7A7, LY96, CFI, DDIT4L, CD14, and IGJ, which may be associated with response to molecules of bacterial origin." (PMID 38218802, 2024). "Further studies found that CFI, DDIT4L, and FAM46C were potential biomarkers in periodontitis and MS." (PMID 38218802, 2024). "Results of immunohistochemical staining revealed that CFI, DDIT4L, and FAM46C were upregulated in periodontitis samples compared with healthy controls." (PMID 38218802, 2024). "Venn diagrams revealed that there were eight shared genes (FAM46C, SLC7A7, LY96, CFI, DDIT4L, CD14, C5AR1, and IGJ) that overlapped between periodontitis and MS which were screened by WGCNA and DEGs." (PMID 38218802, 2024). "qRT-PCR results indicated that mRNA levels of the pro-inflammatory cytokines (IL-1, IL-6, and IL-8) and also CFI, DDIT4L, F4AM6C were upregulated in patients with periodontitis compared with healthy controls." (PMID 38218802, 2024).
anaplastic thyroid cancer (1 paper, 2022). "find tumor suppressor genes, including DDIT4L, that are significantly elevated in the metformin and pioglitazone combination-treated anaplastic thyroid cancer cells." (PMID 35646656, 2022).
Autoimmunity (1 paper, 2015). The occurrence of an immune reaction against the organism's own cells or tissues. "Although the precise role of the encoded protein remains largely unknown, the function of DDIT4L in autoimmunity may be related to the negative regulation of mTOR." (PMID 26057447, 2015).
bronchopulmonary dysplasia (1 paper, 2024). Bronchopulmonary dysplasia is a chronic respiratory disease that results from complications related to lung injury during the treatment of infant acute respiratory distress syndrome in low-birth-weight premature infants or from abnormal lung development in older infants. "Moreover, DDIT4L gene expression in lung macrophages also appeared reduced in infants who developed more severe bronchopulmonary dysplasia (BPD), an inflammatory-associated form of chronic lung disease, compared with infants with mild or no BPD." (PMID 38319716, 2024). "DDIT4L expression during bronchopulmonary dysplasia in preterm infants." (PMID 38319716, 2024). "Further analysis showed that DDIT4L is upregulated in lung macrophages from premature neonates during the neonatal period, with reduced expression of this gene in infants who develop bronchopulmonary dysplasia, suggesting a potential protective role against inflammatory-associated lung injury." (PMID 38319716, 2024).
chronic lung disease (1 paper, 2024). According to the definitions of the American and British Thoracic Societies, including pulmonary functional tests, X-rays, and CT scans for items such as fibrosis, bronchiectasis, bullae, emphysema, nodular or lymphomatous abnormalities. "The observation that DDIT4L expression was reduced in infants who subsequently developed neonatal chronic lung disease further suggests an important biological role of DDIT4L in limiting the exaggerated inflammation during the neonatal transition period." (PMID 38319716, 2024).
colorectal cancer (1 paper, 2013). A primary or metastatic malignant neoplasm that affects the colon or rectum. "In the present study, we found that the expression of DDIT4L was low and it had a hypermethylated promoter in HCT116, but was reactivated in DKO cells, where it showed a decreased methylation level, suggesting an aberrant methylation status of DDIT4L in colorectal cancer." (PMID 23324053, 2013).
diabetes (1 paper, 2024). "The paralogs DDIT4 and DDIT4L have been most extensively studied in skeletal muscle tissue, and DDIT4 has also received considerable attention relating to its role in cancer and diabetes." (PMID 38319716, 2024).
dilated cardiomyopathy (1 paper, 2020). Cardiomyopathy which is characterized by dilation and contractile dysfunction of the left and right ventricles. "DDIT4L is expressed in cardiomyocytes and myocardial tissues of pathologically stressed mice, cultured neonatal rat ventricular myocyte (NRVM) models and patients with dilated cardiomyopathy." (PMID 33062700, 2020).
germinoma (1 paper, 2010). A malignant germ cell tumor arising in the central nervous system. "Six genes (BANK1, CXCL9, CXCL11, DDIT4L, ELOVL6 and HERC5) within 4q13.3-4q28.3 were more abundant in germinomas." (PMID 20178649, 2010).
heart failure (1 paper, 2023). Inability of the heart to pump blood at an adequate rate to meet tissue metabolic requirements. "This evidence further supports the important regulatory role of Ddit4l in the development of heart failure or HFpEF." (PMID 38089628, 2023).
leukemia (1 paper, 2021). A malignant (clonal) hematologic disorder, involving hematopoietic stem cells and characterized by the presence of primitive or atypical myeloid or lymphoid cells in the bone marrow and the blood. "DUX4 (double homeobox 4) plays an essential role in patients’ leukemias carrying the recently described DUX4-IGH (immunoglobulin heavy chain) translocation, while the downstream mediator DDIT4L (DNA-damage-inducible transcript 4 like) is identified as therapeutic vulnerability." (PMID 34580292, 2021).
cancer (5 papers, 2022 to 2025). A tumor composed of atypical neoplastic, often pleomorphic cells that invade other tissues.
tumor (5 papers, 2020 to 2025). "Inducible knockdown of DDIT4L significantly diminished leukemic growth within 2 weeks of in vivo tumor growth, suggesting that downregulation of DDIT4L might have mediated, at least in part, the growth inhibitory effects observed in the shDUX4 population." (PMID 34580292, 2021). "We confirmed a tumor-maintaining potency of the MLL-AF4 fusion protein in PDX models in vivo and used the technique to identify DDIT4L as therapeutic targets in PDX ALL carrying the recently described DUX4-IGH translocation." (PMID 34580292, 2021).
cardiovascular diseases (1 paper, 2023). "This suggests that DDiT4L may be a therapeutic target in cardiovascular diseases when autophagy and mTOR signaling pathways play important roles." (PMID 38089628, 2023).
DDIT4L also shares sentences with these, for which no sentence is quoted: infection (2 papers); arrhythmogenic right ventricular cardiomyopathy (1); arteritis (1); co-infection (1); Glucose intolerance (1); hypertrophic cardiomyopathy (1); ischemia (1); liver cancer (1); multiple sclerosis (1); myocardial infarction (1); myopathy (1); ovarian carcinoma (1); sarcoidosis (1); skin cutaneous melanoma (1); skin tumor (1).